RNF146 (ring finger protein 146)
Description:
E3 ubiquitin-protein ligase that specifically binds poly-ADP-ribosylated (PARsylated) proteins and mediates their ubiquitination and subsequent degradation. May regulate many important biological processes, such as cell survival and DNA damage response. Acts as an activator of the Wnt signaling pathway by mediating the ubiquitination of PARsylated AXIN1 and AXIN2, 2 key components of the beta-catenin destruction complex. Acts in cooperation with tankyrase proteins (TNKS and TNKS2), which mediate PARsylation of target proteins AXIN1, AXIN2, BLZF1, CASC3, TNKS and TNKS2. Recognizes and binds tankyrase-dependent PARsylated proteins via its WWE domain and mediates their ubiquitination, leading to their degradation. Different ubiquitin linkage types have been observed: TNKS2 undergoes ubiquitination at 'Lys-48' and 'Lys-63', while AXIN1 is only ubiquitinated at 'Lys-48'. May regulate TNKS and TNKS2 subcellular location, preventing aggregation at a centrosomal location. Neuroprotective protein. Protects the brain against N-methyl-D-aspartate (NMDA) receptor-mediated glutamate excitotoxicity and ischemia, by interfering with PAR-induced cell death, called parthanatos (By similarity). Prevents nuclear translocation of AIFM1 in a PAR-binding dependent manner (By similarity). Does not affect PARP1 activation (By similarity). Protects against cell death induced by DNA damaging agents, such as N-methyl-N-nitro-N-nitrosoguanidine (MNNG) and rescues cells from G1 arrest (By similarity). Promotes cell survival after gamma-irradiation. Facilitates DNA repair.
Synonyms: DKFZp434O1427; dactylidin; dJ351K20.1
Tractability: Small molecule: a structure with a bound ligand is known. Antibody: its Gene Ontology location is reachable by antibodies, with high confidence; the Human Protein Atlas places it where antibodies can reach. PROTAC: UniProt records ubiquitination sites on it; ubiquitination databases record sites on it; its protein half-life has been measured.
Gene: Protein-coding gene on chromosome 6 (127,266,582 to 127,288,567, forward strand). Ensembl gene ENSG00000118518.
Subcellular location: Cytoplasm, cytosol; Nucleus
Subcellular location (Human Protein Atlas): Cytosol; Plasma membrane; Nucleoplasm
Pathways (Reactome):
Signal Transduction: Degradation of AXIN; Regulation of PTEN stability and activity; TCF dependent signaling in response to WNT
Metabolism of proteins: Ub-specific processing proteases
Gene Ontology:
Molecular function: poly-ADP-D-ribose binding; protein binding; ubiquitin protein ligase activity; ubiquitin-protein transferase activity; zinc ion binding
Biological process: positive regulation of canonical Wnt signaling pathway; protein autoubiquitination; protein K48-linked ubiquitination; ubiquitin-dependent protein catabolic process; protein ubiquitination; Wnt signaling pathway
Cellular component: cytosol; plasma membrane; cytoplasm; nucleus
Genetic constraint (gnomAD): Loss-of-function variants: 10 observed, 28.62 expected, observed/expected ratio (o/e) 0.35, 90% interval 0.22 to 0.59. The upper end of that interval is the gene's LOEUF score, 0.59, which puts it in group 2 of 6, group 1 being the genes least tolerant of losing a copy. Missense variants: 337 observed, 452.87 expected, observed/expected ratio (o/e) 0.74, 90% interval 0.68 to 0.81. Synonymous variants: 148 observed, 164.2 expected, observed/expected ratio (o/e) 0.9, 90% interval 0.79 to 1.03.
Homologues: Orthologues: chimpanzee RNF146 (100% identical), macaque RNF146 (99% identical), pig RNF146 (97% identical), rabbit RNF146 (94% identical), mouse Rnf146 (92% identical), dog RNF146 (91% identical), guinea pig RNF146 (90% identical), rat Rnf146 (90% identical), tropical clawed frog rnf146 (62% identical), zebrafish rnf146 (54% identical), Drosophila melanogaster Rnf146 (32% identical), Caenorhabditis elegans Y105E8A.14 (17% identical), and 1 more.
Diseases named in the same sentence as RNF146 in open-access papers:
RNF146 is named in the same sentence as 28 diseases in open-access papers, as found by Europe PMC text mining. Sharing a sentence is not in itself a finding about the gene and the disease. The quoted sentences say what the papers report.
breast carcinoma (4 papers, 2011 to 2013). "RNF146 is found in a breast cancer susceptibility locus at 6q22.33, with overexpression of the locus but not mutation correlated with increased breast cancer risk in both Ashkenazi Jewish and non-Jewish women." (PMID 23621985, 2013). "Interestingly, the 6q22.33 region has been identified as a breast cancer susceptibility locus where two candidate genes are located, that is, RING finger protein 146 (RNF146) and enoyl coenzyme A hydratase domain-containing 1 (ECHDC1)." (PMID 21958427, 2011). "The chromosomal region of RNF146 has been linked to breast cancer risk in a Jewish Ashkenazi population, although no mutations in the protein coding region have been identified." (PMID 21799911, 2011). "As the majority of BRCA1 cancers are ER-, there is also recent evidence suggesting that E3 ubiquitin-ligases (related family of RNF146, a candidate gene in 6q22.33) and BRCA1 may act in conjunction to regulate ER-mediated pathways in breast cancer tumorigenesis." (PMID 22768030, 2012).
non-small cell lung carcinoma (3 papers, 2014 to 2018). A group of at least three distinct histological types of lung cancer, including non-small cell squamous cell carcinoma, adenocarcinoma, and large cell carcinoma. "RNF146 encodes for a E3 ubiquitin ligase ring finger protein 146, a critical regulator of Wnt/β-catenin signaling, whose overexpression, for example reported in non-small cell lung cancer, enhanced cell growth, invasion, and survival." (PMID 30208867, 2018). "A recent study correlates RNF146 overexpression with invasiveness of non-small cell lung cancer." (PMID 26102504, 2015). "In the present study, the role of RNF146 in non-small cell lung cancer (NSCLC) was investigated." (PMID 24454854, 2014).
Stroke (3 papers, 2017 to 2018). Sudden impairment of blood flow to a part of the brain due to occlusion or rupture of an artery to the brain. "Further investigations are required for a better understanding of the underlying mechanism of the RNF146/autophagy pathway and its significance in cell survival after TBI, stroke or other types of neurological diseases." (PMID 28321181, 2017). "RNF146 has been shown to be neuroprotective against PAR polymerase-1 (PARP1)-induced cell death during stroke." (PMID 29290984, 2017). "RNF146 expression is increased during preconditioning with low-dose H2O2, NMDA, or sublethal short duration stroke." (PMID 29290984, 2017). "For example, RNF146 has been shown to be neuroprotective against DNA damage, N-methyl-D-aspartate (NMDA)-induced excitotoxicity, and stroke, all of which induce neuronal damage via overactivation of PARP1 enzymatic activity and PAR polymer synthesis." (PMID 29290984, 2017).
cherubism (2 papers, 2022 to 2023). Cherubism is a rare, self-limiting, fibro-osseous, genetic disease of childhood and adolescence characterized by varying degrees of progressive bilateral enlargement of the mandible and/or maxilla, with clinical repercussions in severe cases. "Dysregulation of the E3-ubiquitin ligase RNF146-mediated degradation of the adaptor protein 3BP2 (SH3 domain-binding protein 2) causes cherubism, an autosomal dominant disorder associated with severe inflammatory craniofacial dysmorphia syndrome in children." (PMID 36911671, 2023).
colorectal cancer (2 papers, 2011 to 2022). A primary or metastatic malignant neoplasm that affects the colon or rectum. "RNF146 overexpression is frequently detected in colorectal cancer (CRC) and is an independent biomarker for predicting the poor prognosis." (PMID 35721496, 2022). "Lastly, in the colorectal cancer cell line SW480 that also possesses a truncating APC mutation, tankyrase RNAi stabilizes AXIN1, AXIN2, and RNF146 proteins." (PMID 21799911, 2011). "Testing combination RNAi of RNF146 and HUWE1 in colorectal cancer cells may be informative." (PMID 21799911, 2011).
ischemia (2 papers, 2017 to 2018). A hypoperfusion of the BLOOD through an organ or tissue caused by a PATHOLOGIC CONSTRICTION or obstruction of its BLOOD VESSELS, or an absence of BLOOD CIRCULATION. "Others are activated as a part of cell rescue reaction, such as ring finger protein 146 (RNF146, also called IDUNA), involved in DNA repair, which inhibits cell death after ischemia by preventing AIF translocation from the mitochondria." (PMID 30394012, 2018). "When compared with wild-type mice, RNF146-transgenic mice displayed enhanced neurological function after occlusion of the middle cerebral artery, which indicates that RNF146 protects against ischemia-induced neuronal injury." (PMID 28321181, 2017).
Parkinson disease (2 papers, 2017 to 2019). A progressive degenerative disorder of the central nervous system characterized by loss of dopamine producing neurons in the substantia nigra and the presence of Lewy bodies in the substantia nigra and locus coeruleus. "Here we report that RNF146 expression and RNF146 inducers can prevent cell death elicited by Parkinson’s disease (PD)-associated and PARP1-activating stimuli." (PMID 29290984, 2017). "Ring finger protein 146 (RNF146) is an E3 ubiquitin ligase whose activity prevents poly (ADP-ribose) polymerase 1 (PARP1)-dependent neurodegeneration in Parkinson’s disease (PD)." (PMID 30974833, 2019). "However, the molecular mechanism of rhododendrin-induced RNF146 expression is largely unknown and its translational application for the treatment of Parkinson’s disease remains unexplored." (PMID 30974833, 2019).
Alzheimer disease (1 paper, 2011). A progressive, neurodegenerative disease characterized by loss of function and death of nerve cells in several areas of the brain leading to loss of cognitive function such as memory and language. "While RNF146 is expressed in all human tissues examined in one study, expression was upregulated in the brain of Alzheimer's disease patients." (PMID 21799911, 2011).
Anxiety (1 paper, 2023). Intense feelings of nervousness, tension, or panic often arise in response to interpersonal stresses. "Rnf146-overexpressing mice showed basal locomotor activity and anxiety levels comparable to those of eGFP-overexpressing control mice." (PMID 37524878, 2023).
autism spectrum disorder (1 paper, 2023). A spectrum of developmental disorders that includes autism, and Asperger syndrome. "Increased levels of a protein that regulates neuronal signaling pathway, called Rnf146, are associated with social behavior deficits consistent with autism spectrum disorder (ASD) in a mouse model." (PMID 37524878, 2023).
breast tumors (1 paper, 2012). "While sequencing of the subset of breast tumors did not identify any coding SNPs in RNF146 associated with the risk allele, it is likely that there are other non-coding variants correlated with rs2180341 that may explain observed genotype/expression trend." (PMID 22768030, 2012).
dementia (1 paper, 2017). Loss of intellectual abilities interfering with an individual's social and occupational functions. "To determine clinical relevance of RNF146 in PD pathogenesis, we monitored its expression in postmortem brains from PD patients with dementia." (PMID 29290984, 2017).
gastric cancer (1 paper, 2023). A primary or metastatic malignant neoplasm involving the stomach. "Clinicopathological characteristics and tumour expression of RNF146 in gastric cancer patients." (PMID 37555915, 2023).
hepatocellular carcinoma (1 paper, 2022). A malignant tumor that arises from hepatocytes. "Relationship between RNF146 expression and clinicopathologic parameters of patients with hepatocellular carcinoma." (PMID 35721496, 2022).
lung carcinoma (1 paper, 2014). "Overexpression of RNF146 led to upregulated levels of matrix metalloproteinases 2 and 7 and enhanced lung cancer cell invasiveness, events that were mediated by the classical Wnt/β-catenin signaling pathway." (PMID 24454854, 2014). "RNF146 downregulated the expression of Axin in lung cancer cell lines and induced the expression and nuclear distribution of β-catenin." (PMID 24454854, 2014). "The results showed that the expression of RNF146 was increased in clinical lung cancer samples and cell lines." (PMID 24454854, 2014). "Western blot results also revealed correlations between the levels of RNF146 in lung cancer cells and the expression of cell cycle-related regulatory proteins including cyclinD1, cyclinE and CDK4." (PMID 24454854, 2014). "The scratch test and transwell assay results showed that RNF146 enhanced the migration and invasion of lung cancer cells." (PMID 24454854, 2014). "Our data also showed that RNF146 affected the migration and invasion of lung cancer cells, suggesting that RNF146 has multiple functions." (PMID 24454854, 2014). "However, Western blot results indicated that the overexpression of RNF146 in LTE lung cancer cells inhibited the protein expression of Axin and increased the expression of β-catenin (Figure." (PMID 24454854, 2014). "The data suggest that RNF146 might regulate the migration and invasion of lung cancers by regulating MMP2 and MMP7." (PMID 24454854, 2014). "Wnt signaling is regulated by altered expression of various regulatory proteins in lung cancer and RNF146 may be the only one of those regulators." (PMID 24454854, 2014). "In the present study, the roles of RNF146 in lung cancer were investigated." (PMID 24454854, 2014). "Furthermore, Kaplan-Meier survival analysis demonstrated that overexpression of RNF146 was correlated with the survival of lung cancer patients in stage I (P = 0.016)." (PMID 24454854, 2014). "The RNF146 expression level showed correlations with several clinical pathological factors, including tumor size, differentiation level, lymphatic metastasis, pTNM staging, and the prognosis of patients in stage I, which are important factors that represent the potential for lung cancer malignancy." (PMID 24454854, 2014). "The results reveal new roles for RNF146 in the development and progression of NSCLC and identify RNF146 as a potential target for lung cancer treatment." (PMID 24454854, 2014). "In summary, we observed high expression levels of RNF146 in clinical NSCLC samples, consistent with the finding that RNF146 overexpression enhanced the proliferation and invasion of lung cancer cells." (PMID 24454854, 2014). "The data indicated that expression of RNF146 was increased in the clinical NSCLC samples and lung cancer cell lines." (PMID 24454854, 2014).
neuroblastoma (1 paper, 2017). Neuroblastoma (NB) is the most common solid, extracranial childhood tumor. "Since PARP1 activation has been reported in various neurodegenerative models including PD, we evaluated the therapeutic potential of RNF146 expression in neuroblastoma SH-SY5Y cells challenged with PD-related toxins." (PMID 29290984, 2017). "Here we show for the first time that RNF146 expression is indeed sufficient to prevent PARP1-dependent cell toxicity in neuroblastoma PD model cell lines." (PMID 29290984, 2017).
osteoporosis (1 paper, 2022). A condition of reduced bone mass, with decreased cortical thickness and a decrease in the number and size of the trabeculae of cancellous bone (but normal chemical composition), resulting in increased fracture incidence. "Mice lacking RNF146 in macrophages suffer from osteoporosis through activation of 3BP2-mediated hyperosteoclastogenesis, while deletion of RNF146 in osteoblasts leads to abnormal bone and energy metabolism through osteocalcin." (PMID 35362478, 2022).
pancreatic cancer (1 paper, 2021). "In our previous study, we have found that FHL3 participates in Akt/GSK3β pathway-mediated ubiquitination degradation of EMT-TFs, and the E3 ligase RNF146 was firstly reported to interact with FHL3 in pancreatic cancer." (PMID 34150617, 2021).
cancer (12 papers, 2012 to 2025). A tumor composed of atypical neoplastic, often pleomorphic cells that invade other tissues. "Understanding the upstream regulatory signals of RNF146 is crucial for effectively targeting the PARdU pathway and identifying novel strategies for cancer therapy." (PMID 40001540, 2025). "Genes such as PARP1, NAMPT, AIMP2, MCL1, and TOMM20 exhibited widespread amplifications of CNVs in multiple cancers, while genes like RNF146, GPX4, ESR1, CUL4A, and PTEN showed widespread deletions." (PMID 38499384, 2024). "This action competes with RNF146-mediated degradation, leading to stabilization of tankyrase and its binding partner, Angiomotin, a cancer cell signaling protein." (PMID 37938264, 2023). "Several studies have shown that RNF146 can promote the progression of various cancers by activating the Wnt signalling pathway." (PMID 37555915, 2023). "As a PAR-dependent E3 ubiquitin ligase, RNF146 is involved in the beta-catenin signaling pathway in cancer and PARP1 downstream signaling in neuronal death." (PMID 29290984, 2017). "It has been indicated that the newly identified RNF146 substrates basic leucine zipper nuclear factor 1 (BLZF1) and cancer susceptibility candidate 3 (CASC3) are involved in tumor development and cell proliferation." (PMID 24454854, 2014). "TF RNF146 could positively regulate target gene PDX1 to inhibit the proliferation of cancer cells." (PMID 31126066, 2019). "Besides breast tumorigeneis, this significant observation may suggest a broader role of RNF146 in other types of common cancer." (PMID 22768030, 2012). "Targeting the PARdU pathway represents a promising approach for cancer therapy, particularly in malignancies driven by dysregulated components such as TNKS1/2 and RNF146." (PMID 40001540, 2025). "While JNK activity is critical for tumor growth, excessive activation induced by miR-306 and miR-79 drives tumor elimination, highlighting RNF146 as a key modulator in JNK signaling and a potential target for miRNA-based cancer therapies." (PMID 40001540, 2025). "It has been shown in previous studies that the E3 ubiquitin ligases, such as RNF146, TRIM11, TRIM32, TRIM54, TRIM65 and UBE3C promote various cancers by triggering Wnt/β-catenin signaling via degradation of Axin1." (PMID 37379772, 2023). "Taken together, these findings suggest that tankyrase and RNF146 are major up-stream regulators of LKB1-AMPK pathway and provide another focus for cancer and metabolic disease therapies." (PMID 31554794, 2019). "Targeting RNF146-specific deubiquitinase inhibitors to lower RNF146 protein levels could be an effective treatment for HCC and other Wnt-dependent cancers." (PMID 40001540, 2025). "Considering that miR-9, the mammalian homolog of miR-79, is predicted to target mammalian RNF146 and that JNK signaling is highly conserved throughout evolution, it opens up the possibility of developing a new miRNA-based strategy against cancer." (PMID 36222503, 2022).